TAF2 (TATA-box binding protein associated factor 2)
Description:
The TFIID basal transcription factor complex plays a major role in the initiation of RNA polymerase II (Pol II)-dependent transcription. TFIID recognizes and binds promoters with or without a TATA box via its subunit TBP, a TATA-box-binding protein, and promotes assembly of the pre-initiation complex (PIC). The TFIID complex consists of TBP and TBP-associated factors (TAFs), including TAF1, TAF2, TAF3, TAF4, TAF5, TAF6, TAF7, TAF8, TAF9, TAF10, TAF11, TAF12 and TAF13. TAF2 forms a promoter DNA binding subcomplex of TFIID, together with TAF7 and TAF1.
Synonyms: TAFII150; CIF150; TAF2B; MRT40
Tractability: Small molecule: a structure with a bound ligand is known. PROTAC: ubiquitination databases record sites on it; its protein half-life has been measured.
Gene: Protein-coding gene on chromosome 8 (119,730,774 to 119,832,863, reverse strand). Ensembl gene ENSG00000064313.
Subcellular location: Nucleus
Pathways (Reactome):
Gene expression (Transcription): RNA Polymerase II Pre-transcription Events; RNA Polymerase II Promoter Escape; RNA Polymerase II Transcription Initiation; RNA Polymerase II Transcription Initiation And Promoter Clearance; RNA Polymerase II Transcription Pre-Initiation And Promoter Opening
Disease: HIV Transcription Initiation; RNA Polymerase II HIV Promoter Escape; Transcription of the HIV genome
Gene Ontology:
Molecular function: protein binding; transcription cis-regulatory region binding; chromatin binding; RNA polymerase II general transcription initiation factor activity
Biological process: G2/M transition of mitotic cell cycle; mRNA transcription by RNA polymerase II; positive regulation of transcription initiation by RNA polymerase II; regulation of transcription by RNA polymerase II; RNA polymerase II preinitiation complex assembly; transcription initiation at RNA polymerase II promoter; positive regulation of DNA-templated transcription; regulation of DNA repair; response to paraquat
Cellular component: nucleus; transcription factor TFIID complex; transcription factor TFTC complex; nucleoplasm
Genetic constraint (gnomAD): Loss-of-function variants: 51 observed, 116.96 expected, observed/expected ratio (o/e) 0.44, 90% interval 0.35 to 0.55. The upper end of that interval is the gene's LOEUF score, 0.55, which puts it in group 2 of 6, group 1 being the genes least tolerant of losing a copy. Missense variants: 988 observed, 1,341.4 expected, observed/expected ratio (o/e) 0.74, 90% interval 0.7 to 0.78. Synonymous variants: 438 observed, 451.2 expected, observed/expected ratio (o/e) 0.97, 90% interval 0.9 to 1.05.
Homologues: Orthologues: chimpanzee TAF2 (99% identical), macaque TAF2 (99% identical), dog TAF2 (98% identical), rabbit TAF2 (96% identical), rat Taf2 (96% identical), mouse Taf2 (96% identical), pig TAF2 (93% identical), guinea pig TAF2 (88% identical), tropical clawed frog taf2 (82% identical), zebrafish taf2 (82% identical), Drosophila melanogaster Taf2 (47% identical), Caenorhabditis elegans taf-2 (29% identical).
Diseases named in the same sentence as TAF2 in open-access papers:
TAF2 is named in the same sentence as 12 diseases in open-access papers, as found by Europe PMC text mining. Sharing a sentence is not in itself a finding about the gene and the disease. The quoted sentences say what the papers report.
breast carcinoma (2 papers, 2014 to 2024). "TAF2 has been reported to be amplified in breast cancer and CSMD3 as mutated in Esophageal Squamous Cell Carcinoma." (PMID 39457378, 2024). "For Breast cancer 6 genes had significant aCGH/expression correlation at a level of 0.05 in all 7 breast cancer data sets (BCL9, AZIN1, TAF2, YTHDF1, TTC13, FBXL20)." (PMID 25148247, 2014).
Intellectual disability (1 paper, 2019). "Recent exome sequencing studies have produced compelling evidence that pathogenic variants in TAF1, TAF2, TAF8 and TAF13 are linked to intellectual disability and microcephaly." (PMID 30948355, 2019). "First, variants in TAF1, TAF2, TAF8 and TAF13 have all been linked to intellectual disability and microcephaly." (PMID 30948355, 2019).
melanoma (1 paper, 2016). A malignant, usually aggressive tumor composed of atypical, neoplastic melanocytes. "In melanomas, TAFH RNAi induced the differential expression of TBP, TAF1, TAF2, TAF6, TAF10, and TAF12 ASVs." (PMID 27499390, 2016).
ovarian carcinoma (1 paper, 2014). A malignant neoplasm originating from the surface ovarian epithelium. "TAF2 appears to be important in ovarian cancer since it is most frequently altered in HGSC, with amplifications, copy number gains, and mRNA upregulation present in 73% of tumors." (PMID 24653979, 2014). "Further dissection of the role TAF2 plays in ovarian cancer could illuminate whether this TAF regulates alternative transcriptional programs involved in differentiation and proliferation." (PMID 24653979, 2014). "Reminiscent of the TFIID-independent function of TAF3 in regulation of myogenesis, the transcriptional control of Inr-containing promoters by TAF1/TAF2 may be relevant in ovarian cancer, since TBP is predominantly downregulated in many HGSCs." (PMID 24653979, 2014).
ovarian tumor (1 paper, 2014). "For the sake of this discussion, we will focus on TAF2, TAF4, TAF4B, and TAF9 as illustrative examples of how specific TAF subunits may be involved in regulating ovarian tumor properties." (PMID 24653979, 2014).
serous ovarian cancers (1 paper, 2014). "Strikingly, TAF2 exhibits copy number increases or mRNA overexpression in 73% of high-grade serous ovarian cancers (HGSC)." (PMID 24653979, 2014).
cancer (4 papers, 2014 to 2024). A tumor composed of atypical neoplastic, often pleomorphic cells that invade other tissues. "We carried out co-IP assays to examine whether TAF2 associates with the TFIID complex in three independent cancer cell lines." (PMID 38773077, 2024). "Collectively, these results suggested that TAF2 is indispensable for cell survival of multiple cancer cell lines." (PMID 38773077, 2024). "Here, we report that TBP-associated factor 2 (TAF2) specifically regulates TFIID binding to a small subset of protein-coding genes and is essential for cell growth of multiple cancer lines." (PMID 38773077, 2024). "Our cell-based assays have clearly demonstrated a TAF2 dependency for the growth and survival of multiple cancer lines." (PMID 38773077, 2024). "Four riboSNitch-depleted 5′UTRs (ING3, RBM22, NSA2 and TAF2) were detected at the q-value cutoff of 0.05, and all of these elements were cancer-specific." (PMID 31160636, 2019). "In addition, the identified TAF2-bound 1336 peaks were also highly conserved in other tested cancer lines, such as ovarian A2780 and lung H1299 cancer cell lines." (PMID 38773077, 2024). "Although little is known about the role TAF2 might play in cancer, it is required for cell cycle progression in yeast, and expression of yeast TAF2 and several other TAFs is dramatically reduced when cells are induced into a stationary phase." (PMID 24653979, 2014). "DCAF13 was strongly correlated with SLC25A32 in most cancers (R = 0.75), followed by FAM91A1 (R = 0.69) and TAF2 (R = 0.68)." (PMID 39624160, 2024). "Here, we report that TAF2 may exist in only a small fraction of TFIID complexes and is essential for the cell growth of multiple cancer cell lines." (PMID 38773077, 2024). "Our anti-TAF2 antibody was able to immunoprecipitate endogenous TAF2, as well as core subunits of the TFIID complex, including TBP, TAF4, TAF5, TAF6, and TAF7, in nuclear extracts from colorectal HCT116, embryonic kidney HEK-293, and ovarian A2780 cancer lines." (PMID 38773077, 2024).
tumor (2 papers, 2010 to 2014). "At the biochemical level, TAF2 directs TFIID to TATA-less promoters by contact with an Initiator element, which may lead to the deregulation of the transcriptional output of these tumor cells." (PMID 24653979, 2014).
neurological disorders (1 paper, 2015). "From a pharmaceutical point of view, it is to date entirely unclear whether or not neurological disorders caused by mutations in the TAF2 gene develop due to altered regulation of transcriptional activity or due to other currently unknown mechanisms." (PMID 25586196, 2015).
TAF2 also shares sentences with these, for which no sentence is quoted: congenital heart disease (1 paper); esophageal squamous cell carcinoma (1); microcephaly (1).